UGT2B15 (UDP glucuronosyltransferase family 2 member B15)
Description:
UDP-glucuronosyltransferase (UGT) that catalyzes phase II biotransformation reactions in which lipophilic substrates are conjugated with glucuronic acid to increase the metabolite's water solubility, thereby facilitating excretion into either the urine or bile. Essential for the elimination and detoxification of drugs, xenobiotics and endogenous compounds. Catalyzes the glucuronidation of endogenous steroid hormones such as androgens (testosterone, androsterone) and estrogens (estradiol, epiestradiol, estriol, catechol estrogens). Displays glucuronidation activity toward several classes of xenobiotic substrates, including phenolic compounds (eugenol, 4-nitrophenol, 4-hydroxybiphenyl) and phenylpropanoids (naringenin, coumarins). Catalyzes the glucuronidation of monoterpenoid alcohols such as borneol, menthol and isomenthol, a class of natural compounds used in essential oils (By similarity).
Synonyms: UDPGT 2B8; UGT2B8; HLUG4; UDPGT2B15; UDPGTH3
Tractability: Small molecule: a structure with a bound ligand is known; a high-quality ligand is known. Antibody: UniProt predicts a signal peptide or a membrane-spanning region. PROTAC: its protein half-life has been measured.
Target class: Enzyme; Transferase
Gene: Protein-coding gene on chromosome 4 (68,646,597 to 68,670,684, reverse strand). Ensembl gene ENSG00000196620.
Subcellular location: Endoplasmic reticulum membrane
Pathways (Reactome):
Drug ADME: Aspirin ADME; Paracetamol ADME
Metabolism: Glucuronidation
Gene Ontology:
Molecular function: glucuronosyltransferase activity; retinoic acid binding; UDP-glycosyltransferase activity
Biological process: estrogen metabolic process; xenobiotic metabolic process; steroid metabolic process
Cellular component: endoplasmic reticulum membrane
Genetic constraint (gnomAD): Loss-of-function variants: 36 observed, 43.15 expected, observed/expected ratio (o/e) 0.83, 90% interval 0.64 to 1.1. The upper end of that interval is the gene's LOEUF score, 1.1, which puts it in group 4 of 6, group 1 being the genes least tolerant of losing a copy. Missense variants: 610 observed, 581.91 expected, observed/expected ratio (o/e) 1.05, 90% interval 0.98 to 1.12. Synonymous variants: 218 observed, 202.3 expected, observed/expected ratio (o/e) 1.08, 90% interval 0.96 to 1.21.
Homologues: Orthologues: zebrafish ugt2a7 (54% identical), zebrafish ugt2b1 (53% identical), zebrafish ugt2b5 (53% identical), zebrafish ugt5a2 (42% identical), zebrafish ugt5a1 (41% identical), zebrafish si:ch73-334d15.1 (41% identical), zebrafish ugt5b4 (39% identical), zebrafish ugt5g1 (39% identical), zebrafish ugt5c1 (39% identical), zebrafish ugt5b2 (38% identical), zebrafish ugt5g2 (38% identical), zebrafish ugt5c3 (38% identical), and 93 more. Paralogues in human: UGT2B17 (94% identical), UGT2B4 (78% identical), UGT2B7 (78% identical), UGT2B10 (77% identical), UGT2B11 (77% identical), UGT2B28 (76% identical), UGT2A2 (61% identical), UGT2A3 (61% identical), UGT2A1 (52% identical), UGT1A3 (43% identical), UGT1A8 (43% identical), UGT1A1 (43% identical), and 9 more.
Diseases named in the same sentence as UGT2B15 in open-access papers:
UGT2B15 is named in the same sentence as 31 diseases in open-access papers, as found by Europe PMC text mining. Sharing a sentence is not in itself a finding about the gene and the disease. The quoted sentences say what the papers report.
prostate carcinoma (22 papers, 2007 to 2025). A carcinoma that arises from epithelial cells of the prostate gland. "In prostate cancer, miR-331-5p regulates the expression of UGT2B15, a gene correlated with a higher risk of prostate cancer insurgence." (PMID 38540271, 2024). "Most studies indicate that genetic polymorphisms affecting UGT2B15 and/or 2B17 are risk factors for prostate cancer." (PMID 29316660, 2018). "In summary, the results of this meta-analysis suggest that the UGT2B15 D85Y gene variant is protective against prostate cancer." (PMID 28881775, 2017). "Our results showed that all genetic models (additive, dominant, recessive, co-dominant and allele) demonstrated significant association between the UGT2B15 D85Y gene polymorphism and prostate cancer." (PMID 28881775, 2017). "Our meta-analysis revealed a significant association between UGT2B15 D85Y gene polymorphism and prostate cancer in all genetic models (P<0.05)." (PMID 28881775, 2017). "The meta-analysis revealed significant association between the UGT2B15 D85Y gene polymorphism and prostate cancer in all the genetic models (P<0.05)." (PMID 28881775, 2017). "Studies of the association between the UGT2B15 gene D85Y polymorphism and prostate cancer have yielded contradictory results." (PMID 28881775, 2017). "UGT2B15 SNPs rs4148269 and rs3100, were also associated with increased risk for prostate cancer (Log additive model OR = 1.45, 95% CI = 1.03, 2.03; OR = 1.46, 95% CI = 1.08, 1.98, respectively)." (PMID 24267955, 2013). "In prostate cancer studies have focused the UGT2B15(D85Y) and the UGT2B17 gene deletion variants, although a correlation between variations in the gene copy number and serum steroids was also reported." (PMID 24027559, 2013). "On the other hand, UGT2B17 and UGT2B15 alleles that are associated with an increased risk of prostate cancer are more common in Asian populations than in Caucasian populations." (PMID 24106614, 2013). "A SNP cis-acting on UGT2B17 and UGT2B15 expression (rs17147338) was also associated with increased risk of prostate cancer (OR = 1.65, 95% CI = 1.00-2.70); while a stronger association among men with high Gleason sum was observed for SNPs rs4148269 and rs3100." (PMID 24267955, 2013). "All SNPs that showed associations with prostate cancer risk were in Hardy-Weinberg equilibrium in control samples, except for UGT2B15 SNP rs3100." (PMID 24267955, 2013). "We have previously shown that a functional polymorphism of the UGT2B15 gene (rs1902023) was associated with increased risk of prostate cancer (PC)." (PMID 24267955, 2013). "As for the UGT2B15 gene, rs2045100 locus, six SNPs (rs3100, rs4148269, rs9994887, rs13112099, rs7686914 and rs7696472), and rs1902023 polymorphism, showed significant associations with increased risk for prostate cancer." (PMID 38408952, 2024). "UGT2B15 is associated with gastric cancer, breast cancer, and prostate cancer." (PMID 32010623, 2019). "We therefore systematically searched in the PubMed, EMBASE, Science Direct/Elsevier, CNKI, and Cochrane Library databases, and identified six relevant studies with which to perform a meta-analysis of the relation between UGT2B15 D85Y polymorphism and prostate cancer risk." (PMID 28881775, 2017). "To assess whether expression levels of UGT2B enzymes would predict worse prostate cancer outcomes, we analyzed the association between expression of UGT2B15, B17 and B28 in tumor microarrays at the time of radical prostatectomy and risk of BCR." (PMID 28673330, 2017). "Therefore, we systematically reviewed the available literature and performed a meta-analysis to evaluate the association of UGT2B15 D85Y gene polymorphism with prostate cancer risk." (PMID 28881775, 2017). "Subsequently, the resulting phenotype of this UGT2B15 polymorphism is a quicker androgen metabolite clearance which may raise the “effective” amount of steroids within the prostate and decrease risk for prostate cancer." (PMID 24267955, 2013).
prostate carcinoma (continued). "Moreover, studies have demonstrated that the homozygous D85 UGT2B15 (UDP glucuronosyltransferase family 2 member B15) allele genotype could be associated with an increased risk of prostate cancer." (PMID 37181805, 2023). "Previous studies on the transcriptional regulation of UGT2B15 have primarily focused on prostate cancer cells." (PMID 39856707, 2025). "Of interest, the methylation status of prostate cancer cells has a major impact on UGT2B15 and UGT2B17 gene expression." (PMID 35626664, 2022). "Taken together, these results underscore the importance of UGT2B15/B17 in the context of breast and prostate cancer etiology." (PMID 35626664, 2022). "Of interest, genetic variants of the UGT2B15 and UGT2B17 genes were associated differently with prostate cancer risk." (PMID 35626664, 2022). "UGT2B15, as an oncogene, plays a main art in cancer progression, lymph node metastasis, and resistance to therapeutics in prostate cancer." (PMID 35333898, 2022). "Impairment of UGT2B15 is of clinical significance with respect to risks for prostate cancer and renal disorders as well as drug metabolism." (PMID 29316660, 2018). "In this present work, we examined associations between functional SNPs of UGT2B17, UGT2B15 and three other related UGT2B SNPs, and prostate cancer risk among African American and Caucasian men." (PMID 24267955, 2013). "ChIP assays confirm AR binding to UGT2B15 promoters, but the mechanism of androgen suppression in prostate cancer remains unclear." (PMID 39856707, 2025). "It has been recognized that UGT2B15 is only expressed in the AR-positive cell lines and UGT2B15 expression is markedly repressed by AR to sustain pro-proliferative functions of androgen in prostate cancer." (PMID 38136265, 2023). "Interestingly, opposing the tumor suppressive function of UGT2B15 in prostate cancer, our data showed that the expression of UGT2B15 is significantly upregulated in ESCC tissues compared with their matched normal esophageal epithelial tissues." (PMID 38136265, 2023). "Furthermore, UGT2B15 was identified as a negatively-regulated target gene in castration-resistant prostate cancer and lymph node metastases." (PMID 35626664, 2022). "Specifically, the data indicated that UGT2B15 Y85 was protective against prostate cancer." (PMID 28881775, 2017). "Neither UGT2B15 nor UGT2B17 were associated with prostate cancer specific or all-cause mortality (respectively)." (PMID 26646591, 2016). "Upregulation of UGT2B15 in androgen independent prostate cancer has been reported previously." (PMID 17430594, 2007). "Because of limited samples, subgroup analysis could not be performed and therefore, definitive conclusions could not be drawn regarding the clinical value of the UGT2B15 D85Y gene variant in prostate cancer." (PMID 28881775, 2017). "In men, UGT2B15(D85Y) and the UGT2B17 deletion were both associated with alterations in serum steroid levels and fat mass and the UGT215(D85Y) variation has been reported to be associated with increased prostate cancer risk in unselected, Caucasian and Japanese subjects." (PMID 24027559, 2013). "Several groups have reported the importance of miR-376c in downregulating UGT2B15 and UGT2B17 in prostate cancer." (PMID 36741721, 2022). "Within the UGT2 genes, UGT2B15 and UGT2B17 have been broadly investigated in prostate cancer because of their ability to inactive DHT and testosterone." (PMID 33391440, 2021). "UGT2B17 expression has been found to be significantly expressed in prostate cancer metastases and CRPC tumors, while UGT2B15 is negatively regulated in those tissues." (PMID 28673330, 2017). "Several studies have investigated the expression level of UGT2B15 and UGT2B17 in hormone naïve and castration resistant prostate cancer." (PMID 26646591, 2016).
prostate carcinoma (continued). "One recent study has examined the localization of UGT2B15 and UGT2B17 in prostate cancer showing that UGT2B17 increased, and UGT2B15 decreased in cancer progression from benign disease to lymph node metastasis." (PMID 24027559, 2013). "Consequently, UGT2B15 is implicated in diseases associated with androgen imbalances, and modulating its activity could help regulate androgen levels and improve outcomes in conditions such as benign prostatic hyperplasia (BPH), prostate cancer, and other androgen-dependent diseases." (PMID 39856707, 2025). "Thus, UGT2B15 and UGT2B17 expression is negatively regulated by the binding of miR-376c to the 3′-untranslated regions of both genes in prostate cancer cells." (PMID 35626664, 2022). "No study has yet, however, investigated how UGT2B15- or UGT2B17 expression in hormone naïve prostate cancer relates to time to development of CRPC." (PMID 26646591, 2016). "Obviously, the genetic variation in UGT2B17 (and UGT2B15) does not explain the ethnic differences observed in prostate cancer that was discussed previously." (PMID 24106614, 2013). "Elevated circulating testosterone has been associated with UGT2B28 nuclear staining which may decrease expression of UGT2B15 and UGT2B17 since studies show that their expression is elevated in patients and prostate cancer cell cultures treated with antiandrogens." (PMID 28673330, 2017).
breast carcinoma (18 papers, 2007 to 2025). "To this end, we have analyzed the occurrence of polymorphisms in three genes (ESR1, CYP2C19 and UGT2B15) that were earlier shown to have prognostic significance in tamoxifen-treated breast cancer patients." (PMID 23951298, 2013). "We hope that further validation of these results and an attempt to understand basic biological changes driven by increased ESR1 gene dosage as well as by ESR1 PvuII and UGT2B15*2 polymorphisms will contribute to the understanding of breast cancer biology." (PMID 23951298, 2013). "In the present study, we investigated the pharmacokinetics profile and the influence of CYP2D6, CYP2C9, CYP2C19, CYP3A5, POR, ABCB1 and UGT2B15 polymorphisms on the plasma level of tamoxifen and its active metabolites in Ethiopian breast cancer patients receiving adjuvant tamoxifen." (PMID 31547390, 2019). "Data indicate that both hormones inhibited UGT2B15 mRNA levels in endometrial and breast cancer-derived cell lines." (PMID 35626664, 2022). "By the same token, the increased level of UGT2B15 expression exists in some subtypes of breast cancer accompanying a better survival rate." (PMID 35333898, 2022). "In contrast, the hormonal treatment increased UGT2B15 protein levels in both breast cancer cell lines." (PMID 35626664, 2022). "Tamoxifen metabolism pathway was found to be enriched in breast cancer patients involving UGT2B15, SULT1A1 and CYP2D6 genes." (PMID 33503040, 2021). "In breast cancer, UGT2B15 is regulated by sex hormone signaling in estrogen receptor-positive breast cancer." (PMID 32010623, 2019). "Targeting UGT2B15 may provide a therapeutic approach for androgen-related diseases like prostate and breast cancer." (PMID 39856707, 2025). "The expression of UGT2B15 is mainly observed in liver, prostate and breast cancer." (PMID 35109839, 2022). "Both hormones inhibited UGT2B15 mRNA levels in endometrial and breast cancer cell lines." (PMID 35626664, 2022). "Both Net-Cox and fastcox selected UGT2B15, which has a breast-cancer-correlation p = 0.049." (PMID 27378931, 2016). "In a more recent study by Nowell and colleagues, genetic polymorphism in SULT1A1 and UGT2B15 was analysed in patients with breast cancer treated with or without tamoxifen." (PMID 17244352, 2007). "In our study, UGT2B15*2 A/C is likely to have a clinically significant impact on recurrence risk, CYP3A5∗3 A/G on endometrial hyperplasia, and SULT1A1∗2 G/A, and ESRA V364E on vaginal bleeding in Chilean patients with breast cancer who receive tamoxifen adjuvant therapy." (PMID 34899282, 2021). "Contrary to the stimulation observed with estrogens and androgens in breast cancer cells, DHT and synthetic androgens (R1881) inhibit UGT2B15 expression and activity in LNCaP cells." (PMID 39856707, 2025). "The expression and regulation of UGT2B15 and UGT2B17 by steroid hormones were recently measured in breast cancer specimens and cell lines." (PMID 35626664, 2022). "Similar mechanisms whereby UGT2B15 and UGT2B17 influence survival through modulating the androgen signalling pathway have been reported in androgen-sensitive prostate and breast cancer." (PMID 33202946, 2020). "Prior research in multiple ER-positive breast cancer cell lines has shown that FOXA1, functioning as a pioneering transcription factor, aids in opening chromatin and then attracting AR or ER to nearby promoter regions of UGT2B15 genes." (PMID 39856707, 2025).
breast carcinoma (continued). "In addition, we have shown that UGT2B15 and UGT2B17 are prognostic in specific molecular subtypes of breast cancer as defined by the METABRIC (Molecular Taxonomy of Breast Cancer International Consortium) project." (PMID 34503303, 2021). "This is the case for UGT2B7 induced by several anti-cancer agents in liver cell models, for UGT2B15 induced by tamoxifen and UGT2B17 induced by exemestane in breast cancer-cell models, as well as for UGT1A4 induced by fulvestrant in breast cancer and liver cell models." (PMID 32047295, 2020). "In the present study we investigated the prognostic and/or predictive value of functional polymorphisms in cytochrome P450 3A5 CYP3A5 (*3), CYP2D6 (*4), sulphotransferase 1A1 (SULT1A1; *2) and UDP-glucuronosyltransferase 2B15 (UGT2B15; *2) in tamoxifen-treated patients with breast cancer." (PMID 17244352, 2007).
gastric cancer (4 papers, 2019 to 2024). A primary or metastatic malignant neoplasm involving the stomach. "Notably, UGT2B15, previously associated with pathogenesis and prognosis of gastric cancer and HEPACAM2, upregulated in patients with poor prognosis and linked to metastasis in various types of cancer, were highlighted." (PMID 39123475, 2024). "Additionally, it is previously reported that UGT2B15 is enhanced in gastric cancer." (PMID 35333898, 2022). "Bioinformatic analysis suggests that UGT2B15 activates the Hippo‐YAP signalling pathway, leading to the pathogenesis of gastric cancer." (PMID 35109839, 2022). "UGT2B15 may upregulate FOXA1 and activate the hippocampal-yap signaling pathway to promote the development of gastric cancer." (PMID 32010623, 2019).
Anxiety (3 papers, 2018 to 2023). Intense feelings of nervousness, tension, or panic often arise in response to interpersonal stresses. "Specifically, whereas homozygous male carriers of the UGT2B15*2 variant had a lesser reduction in anxiety compared to placebo, female patients with the same genotype experienced greater anxiety reduction due to lorazepam premedication." (PMID 37239455, 2023). "Herein, we discuss recent findings regarding the pharmacogenetics of uridine 5'-diphosphate-glucuronosyltransferase 2B15 (UGT2B15), lorazepam, and its role in the treatment of anxiety." (PMID 30443442, 2018).
colorectal cancer (2 papers, 2017 to 2022). A primary or metastatic malignant neoplasm that affects the colon or rectum. "In a study of 1600 colorectal cancer patients and 2500 unaffected siblings, the variation in 4 UGT genes (UGT1A3, UGT1A6, UGT2B4, and UGT2B15) modified risk of colorectal cancer either independently of interactively with nonsteroidal anti-inflammatory use." (PMID 27881391, 2017).